IL6 (interleukin 6)
Diseases named in the same sentence as IL6 in open-access papers (continued):
Sharing a sentence is not in itself a finding about the gene and the disease.
delirium (continued). "In the current research, pre-infusion of HS reduced the levels of IL-6, TNF-α and S100β compared with normal saline group, which is in accordance with prior studies that found higher levels of S100β in patients with delirium than in patients without delirium." (PMID 38082215, 2023). "Within-subject analysis showed that levels of IL-6, IL-10 and MCP-1 decreased significantly over time in both groups, but were not different between patients with and without delirium." (PMID 29801516, 2018). "There were markers in both serum and CSF that differed between the affected and non-affected patients (SCI; IL6, GFAP, CSPG4, delirium; TR4, EZH2, hallucinations; NF1)." (PMID 30367354, 2018).
epilepsy (174 papers, 2009 to 2026). A brain disorder characterized by episodes of abnormally increased neuronal discharge resulting in transient episodes of sensory or motor neurological dysfunction, or psychic dysfunction. "Overall, the massive expression of IL-6 in epilepsy is undoubtedly a hallmark of central immune activation, and its main effects tend to enhance neuroexcitation and exacerbate seizures." (PMID 41306289, 2025). "Proinflammatory cytokines, such as IL-1b and IL-6, have been shown to be increased in several studies on epilepsy, with IL-6 associated with seizure severity." (PMID 40591616, 2025). "Activation of the IL-6 pathway is implicated in the progression of epilepsy, neuroinflammation and BBBD." (PMID 38348743, 2024). "Increased production of IL-6 and its association with epileptic disease profiles are well established, suggesting the presence of chronic systemic inflammation in epilepsy." (PMID 37025699, 2023). "In the context of epilepsy, elevated levels of IL-6 in both brain and plasma have been implicated in the severity of seizures in both patients with epilepsy conditions and animal studies." (PMID 36997619, 2023). "The downregulated expression of IL-6 and the upregulated expression of IL-12p40 combine to create a risk for epilepsy as a comorbidity of autism." (PMID 36819340, 2023). "Increased circulatory concentrations of IL-6 are associated with high GADA titers in patients with epilepsy." (PMID 37025699, 2023). "In vivo studies also proved that activated glial cells produce large amounts of proinflammatory cytokines such as TNF-α, IL-1β, and IL-6, which, in turn, cause neuronal damage in the hippocampus of rats with epilepsy." (PMID 35456948, 2022). "The experimental group revealed a decrease in inflammatory markers: high-mobility group protein B1, matrix metalloproteinase-9, and interleukin-6, which have been implicated with poststroke epilepsy." (PMID 36338344, 2022). "Recent studies suggest that inflammatory mediators, such as interleukin- (IL-) 1β, IL-6, and IL-10, play a significant role in the underlying pathophysiology of epilepsy, contributing to the onset and perpetuation of seizures." (PMID 33959658, 2021). "Taken together, IL-6 appears to have numerous roles in neuronal homeostasis, and its elevation is clearly associated with increased-seizure susceptibility and epilepsy." (PMID 32552898, 2020). "The Ala16Val MnSOD polymorphism also revealed a significant importance when associated with the genotype: the VV epilepsy group demonstrated increased levels of IL-6 and caspase-3 when compared to other genotypes (AV and AA)." (PMID 32219137, 2020). "The novel finding of the study is the influence of Ala16Val MnSOD gene polymorphism-VV genotype on inflammatory (IL-6, IL-1β), apoptotic (caspases -1 and -3) and antioxidant enzyme (MnSOD) in epilepsy." (PMID 32219137, 2020). "Inflammation has been implicated in the pathophysiological events of both epilepsy and life-threatening ventricular arrhythmia, in which the central role of the interleukin-6 (IL-6) is well recognized." (PMID 28649227, 2017). "Taken together, there is compelling evidence that increased levels of IL-6 are deeply involved in the pathophysiological mechanisms underlying both epilepsy and cardiac diseases." (PMID 28649227, 2017). "Inflammation has been implicated in the pathogenesis of both epilepsy and ventricular arrhythmia, with interleukin-6 (IL-6) being recognized as a crucial orchestrator of inflammatory states." (PMID 28649227, 2017). "A meta-analysis further showed that two alleles of proinflammatory cytokines (IL-1α-889 and IL-1β-511) and the serum concentration of IL-6 were significantly associated with epilepsy." (PMID 27882059, 2016). "In our study, serum interictal IL-6 concentration was the only one associated with all seizure severity evaluation scales in all three types of epilepsy." (PMID 26626560, 2015).
epilepsy (continued). "Further studies are also required to investigate the exact mechanisms underlying the action of IL-6 in epilepsy." (PMID 24348794, 2014). "In addition, increased circulatory concentrations of IL‐6 are associated with high glutamic acid decarboxylase antibodies (GADA) titers in patients with epilepsy, further elucidating immune mechanisms in GADA‐associated autoimmune epilepsy." (PMID 40103702, 2025). "Given that excessive production of TNF‐α, IL‐6, and IL‐1β has been implicated in neurodegenerative diseases and epilepsy, our findings suggest that Listerin may serve as a protective factor against pathological neuroinflammation." (PMID 40448625, 2025). "We have also demonstrated that neuroinflammation was induced in febrile seizures, and the increased pro‐inflammatory factors, such as interleukin 1β (IL‐1β) and IL‐6, might be responsible for the epileptogenesis in fever‐associated epilepsy." (PMID 38357846, 2024). "IL-6 gene polymorphisms have also been implicated in pediatric epilepsy and febrile seizure cases." (PMID 32552898, 2020). "Similarly, serum levels of IL-6 have been associated with a range of human epilepsy conditions, and it is generally regarded as being ictogenic in this context." (PMID 31717556, 2019). "This study suggests that chronic oil fish supplementation has a protective anti-inflammatory effect against elevated levels of IL-6 in the heart of rats with epilepsy, but the underlying mechanisms of these effects remain unknown." (PMID 28649227, 2017). "In multivariate analysis, it was positively linked to severity of all three types of epilepsy, indicating that serum IL-6 may be a good candidate to indicate seizure severity in general." (PMID 26626560, 2015). "In epilepsy patients, the serum IL-6 level during the interictal period was significantly higher than that in the normal population." (PMID 39858450, 2025). "IL-1β and IL-6 transcript levels were still significantly elevated up to 7 weeks post-SE during the chronic phase of epilepsy." (PMID 41445743, 2025). "Peripheral blood mononuclear cell (PBMC) stimulation studies in patients with epilepsy demonstrated a hyper‐reactive immune state with increased IL‐1 family cytokines, IL‐6, IL‐10, and IFN‐α compared to controls." (PMID 40729436, 2025). "Studies of inflammatory mediators in other seizure disorders have found increased IL‐6 expression in resected tissue in focal cortical dysplasia and tuberous sclerosis." (PMID 40729436, 2025). "Clinical studies have found that the expression levels of IL‐1β,20 IL‐6,21 IL‐18,20, 22 and IL‐33 23 in the serum of epilepsy patients are elevated." (PMID 40103702, 2025). "Under normal physiological conditions, IL-6 expression in the brain is extremely low; however, IL-6 levels are significantly elevated in cerebrospinal fluid and serum of patients with epilepsy." (PMID 41306289, 2025). "Elevated PIC levels are consistently observed during epileptic seizures, with IL-6 demonstrating persistent upregulation across diverse epilepsy subtypes- even during interictal and postictal phases." (PMID 40880740, 2025). "The particularly strong suppression of IL-6 by Boldo is noteworthy, as this cytokine is known for its persistent elevation during chronic inflammatory states, including epilepsy." (PMID 41353162, 2025). "A related study found that higher levels of IL-6 and TNF-α in the serum were closely related to increased susceptibility to epilepsy." (PMID 39858450, 2025). "In epilepsy, IL-6 makes brain cells more excitable by increasing N-methyl-D-aspartate (NMDA) receptor activity and weakening gamma-aminobutyric acid (GABA)’s calming effects." (PMID 40941042, 2025). "To this end, we analyzed the transcript levels of the inflammasome mediators Il1β, Il6, Il12, Il10, Tnfα, Cd68, Ccl2, and Ccl5, which are upregulated in pilocarpine‐ and kainic acid‐induced epilepsy models." (PMID 40608247, 2025).
epilepsy (continued). "Some studies have found that mice with complete knockout of the IL-6 gene instead show increased oxidative stress, neuronal damage, and increased mortality in epilepsy models." (PMID 41306289, 2025). "A study further showed that patients with epilepsy had higher IL-1 and IL-6 levels than controls and had a decrease in serum IL-1 and IL-6 levels after surgery." (PMID 40843195, 2025). "IL-6 is another pro-inflammatory cytokine closely related to epilepsy and is widely present in central and peripheral immune responses." (PMID 41306289, 2025). "Clinically, the serum levels of IL-1β, IL-6, and IL-1Ra are significantly elevated in patients with epilepsy." (PMID 40170730, 2025). "The elevation of inflammatory mediators, including IL-1β, TNF-α, and IL-6, was initiated 2 h following seizures and increased to the highest concentration between 6 and 12 h following seizures in the epilepsy mouse model." (PMID 39723425, 2024). "As a result, our further screening demonstrated that pro-inflammatory cytokines (PICs), such as IL-1β, IL-6, and TNF-α, and the TLR4/NF-κB pathway were associated with APS' effects in treating epilepsy." (PMID 38405667, 2024). "Regarding anti-cytokine agents for the treatment of epilepsy, the efficacy of using anti-IL-1 and anti-IL-6 to control seizures in drug-resistant epilepsy and refractory status epilepticus has been reviewed." (PMID 39765588, 2024). "Refractory epilepsy patients had remarkably increased levels of IL‐6 in their serum in comparison to healthy people." (PMID 38361811, 2024). "Compared to the healthy volunteers, epilepsy patients had significantly increased serum levels of the inflammatory factors IL-6, IL-1β, TNF-α, and CRP (P < 0.05), while SIRT3 levels were significantly decreased." (PMID 39091611, 2024). "Follow-up studies have found that serum IL-1β and IL-6 levels in the central and peripheral regions of patients with drug-resistant epilepsy decreased at 1 year after surgical treatment compared with those before surgery." (PMID 39206290, 2024). "Elevated levels of IL‐1β, IL‐6, IL‐9, and TNF‐α have been linked to the subsequent onset of epilepsy in children who experienced acute seizures." (PMID 38361811, 2024). "Our findings also demonstrated that serum SIRT3 levels were negatively correlated with inflammatory factors IL-6 in epilepsy patients." (PMID 39091611, 2024). "CXCL11 levels and VEGFA levels increased the risk of epilepsy, CXCL1 levels, CXCL9 levels, IL-6 levels, TRAIL levels, and VEGFA levels were associated with an increased risk of FE and TTNFSF14 levels, VEGFA levels were associated with an increased risk of GE." (PMID 39315097, 2024). "With the activation of astrocytes, the influential pro-inflammatory cytokine IL-1β induces the generation of IL-6 and TNF-α, both of which are strongly linked to epilepsy." (PMID 39598325, 2024). "Studies have indicated that IL-6 is overexpressed in the brain tissue of patients with epilepsy and is released into circulation through cerebral blood vessels." (PMID 39450173, 2024). "Increased pro‐inflammatory cytokines including tumor necrosis factor‐alpha (TNF‐α), IL‐1β, and IL‐6 were also observed in an epilepsy mouse model with Gabrg2+/Q390X knockin, indicating neuroinflammation was one of the mechanisms for genetic epilepsy." (PMID 38357846, 2024). "Many studies have shown that inflammation is associated with the development of epilepsy, and RA is an autoimmune inflammatory disease in which upregulation of the inflammatory cytokines TNF-α, IL-1, and IL-6 is closely related to pathogenesis." (PMID 38817604, 2024). "Upon pathological changes like epilepsy occurring, IL-6 secretion capacity will be enhanced by the activated microglia." (PMID 37989981, 2024). "We have identified six feature genes (IL6, PTGS2, HMOX1, NFE2L2, TLR4, and JUN) strongly associated with ferroptosis in epilepsy, suggesting their potential as biomarkers for the diagnosis of temporal lobe epilepsy." (PMID 37946105, 2023).
epilepsy (continued). "Compounding evidence suggests a correlation between epilepsy and inflammatory factors, for instance, cyclooxygenase-2, interleukin-1β, and interleukin-6." (PMID 37470000, 2023). "High levels of IL-6 was observed in patients with epilepsy, suggesting that IL-6 is important for the development of epilepsy." (PMID 38074156, 2023). "In this research, we identified six characteristic genes associated with ferroptosis in epilepsy: NFE2L2, PTGS2, IL6, JUN, HMOX1, and TLR4." (PMID 37946105, 2023). "In CSF and serum of epilepsy patients, IL-6 levels were shown to correlate with the severity of seizures, but we have not found any relationship between the presence of spontaneous seizures and Il6 expression in the rat brain in the chronic period after SE." (PMID 37047481, 2023). "ROS and inflammatory factors, primarily TNF-α and IL-6, result in nervous system insults via induction of inflammation and ER stress in brain tissues, which subsequently increase the risks of epilepsy." (PMID 38074156, 2023). "The pro-inflammatory cytokine interleukin-6 (IL-6) has been found to be increased in cerebrospinal fluid and serum after severe generalized tonic clonic seizures in adult patients with epilepsy." (PMID 36895367, 2023). "IL-6 is a protective cytokine, and some studies have found that in certain epilepsy patients, seizure activity is related to an inflammatory response within the body." (PMID 37946105, 2023). "During epilepsy, inflammatory activation of glial cells leads to the production of interleukin-1-beta, interleukin-6, and TNF-α, which are able to perpetuate inflammation to other neurons and recruit adaptive immune response cells in the brain." (PMID 36138769, 2022). "Noteworthy, the blockade of Kv1.3 attenuated KA-induced epilepsy and inhibited microglial activation and the release of proinflammatory cytokines (such as IL-1β, IL-6, and TNF-α) through the Ca2+/NF-κB signaling pathway." (PMID 36499018, 2022). "Patients with epilepsy have shown elevated blood levels of IL-6 both interictally and postictally, as well as elevated CSF levels of IL-6." (PMID 35625063, 2022). "The previous report has revealed that an increased level of IL6 was observed in cerebrospinal fluid and serum from patients with epilepsy." (PMID 36389252, 2022). "Remarkably, taken into consideration the clinical features, the KDM5CHigh subgroup showed an interesting correlation between the epilepsy outcome and high co-expression of Ki67 and IL6." (PMID 36142158, 2022). "In the present study, TNF-α, IFN-γ and IL-6 levels increased in the epilepsy models, while IL-10 and TGF-β2 levels decreased, and these effects were reversed by HsTx2 treatment." (PMID 36457055, 2022). "Interleukin-6 (Il6) is a prototypical proinflammatory cytokine for maintaining homeostasis, and animal experiments showed the involvement of cytokines in epilepsy." (PMID 36389252, 2022). "Previous findings provide strong support for the involvement of pro-inflammatory cytokines in the pathophysiology of epilepsy with elevated levels of the pro-inflammatory cytokines IL-1β, IL-6, IL-10, IL-17, IFN-α, and TNF-α." (PMID 34791253, 2022). "For example, increased concentrations of serum IL-1b, IL-1Ra, IL-2, IL-4, IL-6, IL-8, IFNy and IL-17 have been observed in patients with epilepsy, as well as increased levels of IL-6 and IL-17 in the cerebrospinal fluid." (PMID 34069567, 2021). "The results of the ROC curve showed that the possibility of predicting epilepsy recurrence by IL-6 was 70%." (PMID 33959658, 2021). "Among them, interleukin (IL)-6, IL-1beta, and IL-1 receptor antagonists are the most commonly studied cytokines in epilepsy due to their potent roles in seizure activity." (PMID 34215817, 2021). "HDAC5 silencing or miR-485 mimic reduced the formation of IL-1β, TNF-α, and IL-6 by epilepsy model neurons, and this effect was rescued by HDAC5 overexpression." (PMID 34021541, 2021).